UHRF1 (ubiquitin like with PHD and ring finger domains 1)
Diseases named in the same sentence as UHRF1 in open-access papers (continued):
Sharing a sentence is not in itself a finding about the gene and the disease.
cancer (continued). "TQ-induced upregulation of TSGs in cancer could be attributed in large part to the inhibitory effects of TQ on the UHRF1/DNMT1/HDAC complex, with subsequent apoptosis induction." (PMID 33922029, 2021). "We also demonstrated that the expression of UHRF1, SMUG1, TDG, and MBD1/2/3 presented the most significant positive correlation with other regulators and might be the risk factors for carcinoma formation." (PMID 34552879, 2021). "Well known in cancer development, but unknown in host–pathogen interactions, we show the role played by UHRF1 during Toxoplasma parasitic infection." (PMID 31492965, 2020). "UHRF1 coordinates epigenetic silencing of tumor suppressor genes and plays a key role in cell cycle, epigenetic regulation in the development and progression of cancers and metastasis." (PMID 31492965, 2020). "To test this hypothesis, we analyzed the relationship between UHRF1 expression and immune infiltration levels in 8 types of cancer using TIMER." (PMID 31442209, 2019). "We showed that 2i also regulates UHRF1/DNMT1 expression in cancer cells." (PMID 30696879, 2019). "Our results suggest that cancer cells also require UHRF1 to maintain DNA methylation." (PMID 31064417, 2019). "Moreover, because the inhibition of UHRF1 leads to DNA demethylation by suppressing the recruitment of DNMT1 to newly synthesized hemi-methylated DNA, substantial numbers of cancer cells retain hemi-methylated DNA after UHRF1 depletion." (PMID 31064417, 2019). "Indeed, considering that DNMT3A is involved in de novo DNA methylation, an increase of UHRF1 through the targeting of DNMT3A also likely contributes to the global DNA hypomethylation in cancer cells." (PMID 30669400, 2019). "Although URHF1 mediates cross-talk between DNA methylation and histone acetylation through interaction with DNMT1 and HDAC1, HDACs may nonetheless be recruited to the silenced genes in the UHRF1-depleted cancer cells." (PMID 31064417, 2019). "The UHRF1 protein also has some beneficial functions in cancer." (PMID 31245293, 2019). "UHRF1 is up-regulated in various human cancers and predicts poor prognosis." (PMID 31442209, 2019). "UHRF1 antagonism is emerging as a therapeutic strategy in cancer." (PMID 31481468, 2019). "In that context, our present findings suggest UHRF1 may be an effective therapeutic target for sensitizing cancer cells to antitumor agents." (PMID 31064417, 2019). "The E3 ligase activity of the ring domain of UHRF1 promotes ubiquitination-mediated degradation of the promyelocytic leukemia (PML) protein, a tumor-suppressor protein implicated in tumorigenesis in multiple forms of cancer." (PMID 29899856, 2018). "In the following examples, we will briefly discuss the role of UHRF1 in various types of cancer." (PMID 29899856, 2018). "As these biological processes can directly affect cell survival and death, UHRF1 targeting may be exploited to improve the current cancer therapy." (PMID 29415984, 2018). "Notably, the first in vitro studies of newly discovered UHRF1 inhibitors have shown encouraging results in several cancer cell lines." (PMID 29507645, 2018). "Therefore, it is of high interest to decipher the mechanism of UHRF1 down-regulation putatively highlighting new strategies of TSGs re-expression and thus of anti-cancer therapies." (PMID 29983883, 2018). "Furthermore, UHRF1 overexpression seems to be a common feature in many malignancies and has therefore been suggested as a universal biomarker for cancer." (PMID 29507645, 2018). "As ATC is defined as a cancer with high growth and metastasis ability, we supposed that the overexpressed UHRF1 might be due to the low expression of tumor-suppressive microRNAs in these high metastasis cancers." (PMID 30174788, 2018).
cancer (continued). "Interestingly, always when UHRF1 is down-regulated through the use of natural anti-cancer compounds, TSGs are expressed again with subsequent induction of apoptosis." (PMID 29983883, 2018). "Small molecules binders of SRA domain of UHRF1 would be useful components of molecular toolbox for the study of cancer epigenetics, cell signaling pathways, and most significantly as lead molecules for the development of anti-cancer therapeutics." (PMID 29899856, 2018). "Luteolin is likely to act as an anti-cancer agent by interaction with multiple cellular targets, and it is more than likely that luteolin may directly interact with UHRF1 by binding to the SRA domain." (PMID 29899856, 2018). "UHRF1 was overexpressed in the taxane-resistant cancer cells, which maintained CSC characteristics." (PMID 29752436, 2018). "By its original structure, UHRF1 could be the “driver” of this complex to duplicate the epigenetic code after DNA replication and allows cancer cells to maintain gene repression, and in particular that of TSGs." (PMID 29983883, 2018). "However, during tumorigenesis UHRF1 promotes proliferation of cancer cells and is abundantly expressed throughout cell cycle." (PMID 29899856, 2018). "Taken together, our results showed that TQ selectively induced a rapid UHRF1 auto-ubiquitination in cancer cells, which could be a result of HAUSP down-regulation." (PMID 29983883, 2018). "UHRF1 down-regulation induces reactivation of TSGs and apoptosis in cancer cells." (PMID 29983883, 2018). "Furthermore, the UHRF1 levels in these cancers were inversely correlated with the expression of microRNAs, and restoration of the microRNAs decreased the expression of UHRF1 by targeting of its 3’-UTR directly." (PMID 30174788, 2018). "Therefore, UHRF1 has attracted considerable attention as a potential anti-cancer drug target and universal cancer biomarker." (PMID 29899856, 2018). "Similarly, high levels of UHRF1 mRNA were reported in 160 HCC patients notably during later stages II & III of cancer." (PMID 28881702, 2017). "UHRF1 overexpression is found in majority, if not all, of cancers, thus predicting UHRF1 as an independent universal diagnostic and prognostic biomarker for cancer detection, disease progression and therapeutic response monitoring." (PMID 28881702, 2017). "Such role for UHRF1 might be specific to spontaneously transformed and/or cancer cell lines in which UHRF1 may only be a member of a larger deregulated pathway." (PMID 28587163, 2017). "In cancer cells, UHRF1 is frequently found to be overexpressed constitutively, and the molecular mechanisms underlying UHRF1 overexpression are largely unknown except for a few cases where UHRF1 expression is driven by deregulated miRNAs." (PMID 28467809, 2017). "The abnormally high level of UHRF1 may result from the aberrant activity of various transcription factors regulating the expression of UHRF1 in cancers." (PMID 28881702, 2017). "Ratio of Ki67-staining vs UHRF1-staining might differentiate well between normal proliferating cells and cancer cells." (PMID 28881702, 2017). "Moreover, KISS1, functioning as a metastasis suppressor in various cancers, also looks to be under the control of UHRF1." (PMID 28881702, 2017). "In addition, because UHRF1 is upregulated in many types of cancer cells, it has been considered an oncogene or a prognostic marker for cancer patients." (PMID 28584306, 2017). "However, UHRF1 overexpression is a better diagnosis and prognostic biomarker in cancers as compared with Ki67 and PCNA since it fulfills the requirement of an independent factor." (PMID 28881702, 2017).
cancer (continued). "As experimentally induced UHRF1 gene knockdown in cancer cell lines leads to suppressed growth, the UHRF1 protein is essential for malignant cell’s proliferation and accordingly could be an attractive drug target." (PMID 28128913, 2017). "Similarly, in non-muscle-invasive bladder cancer (NMIBC) increased expression of UHRF1 was found in cancer cells, which was directly related with tumor malignancy." (PMID 28881702, 2017). "Expression of UHRF1 was found significantly increased in the cancer cells and was positively correlated with histological and pathological grade, as higher expression was observed in later stages of cancer." (PMID 28881702, 2017). "However, further studies are warranted to define the differences between upregulation and downregulation of UHRF1 in increasing migratory and invasive properties of cancer cells." (PMID 28584306, 2017). "Considering that USP7 is upregulated in many cancers, this might be one of the possible reason for high levels of UHRF1 in cancer cells." (PMID 28881702, 2017). "Furthermore, we present evidence that UHRF1 deficiency leads to the induction of EMT by activating the CXCR4/AKT-JNK/IL-6 signaling pathway, thereby contributing to the expansion of cancer stem-like cells." (PMID 28584306, 2017). "UHRF1 overexpression relates to tumor size, metastasis, stages of cancer and low survival rate." (PMID 28881702, 2017). "Moreover, cancer cells with UHRF1 overexpression present enhanced rates of growth and migration and morphologic features resembling epithelial mesenchymal transition (EMT)." (PMID 27507047, 2016). "Note that we could not directly evaluate the scope of DNA hypomethylation induced by overexpressed UHRF1 in cancer cells, because UHRF1 is also required for DNA maintenance methylation by DNMT1 and knockdown of UHRF1 compromises DNA methylation by DNMT1." (PMID 27462454, 2016). "Thus, understanding the molecular mechanisms involved in UHRF1 regulation will allow us to find new targets in order to inhibit the expression of UHRF1 allowing cancer cells to undergo apoptosis through a re-expression of tumor suppressor genes." (PMID 27839516, 2016). "In sunitinib-treated RCC tissues, loss of antitumor miR- 101 may lead to upregulation of UHRF1 and EZH2, and consequently, post-transcriptional modification of multiple genes would promote cancer-related phenotypes in cells." (PMID 27487138, 2016). "In this regard, UHRF1 has been reported to be frequently overexpressed in cancers." (PMID 27462454, 2016). "Several studies have explored the potential roles of UHRF1 in cancer development." (PMID 26884069, 2016). "Also in agreement with the observed widespread overexpression of UHRF1 in cancers, our data suggest that UHRF1 is likely to have a broader role in negative regulation of DNMT3A than UHRF2." (PMID 27462454, 2016). "Furthermore, our studies with cancer cell lines demonstrated that UHRF1/2 actively downregulates DNMT3A in all cancer cell lines tested." (PMID 27462454, 2016). "Our data support the past studies of UHRF1 in cancer research, suggesting UHRF1 plays essential roles in BC cell progression and might be a molecular target for BC treatment." (PMID 27072587, 2016). "Our results suggest that UHRF1 is a key epigenetic regulator of DNA methylation and might be a potential target for cancer treatment." (PMID 27507047, 2016). "UHRF1 is an oncogenic factor that is overexpressed in numerous cancers." (PMID 26884069, 2016). "The large quantities of UHRF1 produced in cancers could be result from abnormalities in the upstream regulatory mechanisms of UHRF1." (PMID 27839516, 2016). "To test if UHRF1/2 overexpression indeed leads to downregulation of DNMT3A proteins in cancers despite DNMT3A overexpression at the level of transcription, we next examined the levels of UHRF1, UHRF2 and DNMT3A proteins in paired lung tumors and adjacent normal controls by western blot analysis." (PMID 27462454, 2016).
cancer (continued). "We next wished to test whether negative regulation of DNMT3A by UHRF1/2 contributes to DNA hypomethylation in cancer." (PMID 27462454, 2016). "Since UHRF1 is over‐expressed in several other cancers, its ability to regulate Keap1–Nrf2 may be important in their pathogenesis." (PMID 26497117, 2016). "In the same context, we have shown that the natural anti-cancer drug, epigallocatechin-3-gallate (EGCG) induces a significant decrease in UHRF1 and DNMT1 expression in Jurkat cells in association with p16INK4A upregulation, cell cycle G1/S arrest and apoptosis." (PMID 27839516, 2016). "As UHRF1 is also required for DNA maintenance methylation, we could not manipulate the level of UHRF1 in cancer cell lines to test whether negative regulation of DNMT3A by UHRF1 contributes to DNA hypomethylation in cancer." (PMID 27462454, 2016). "This demonstrates that the relation between miR-146a-5p and UHRF1 may be a key axis in metastasis across carcinomas, including ccRCC as shown for the first time in our study." (PMID 26859141, 2016). "Previous studies suggest that UHRF1 is overexpressed in different types of cancers." (PMID 25765655, 2015). "UHRF1 expression levels are correlated with cancer metastasis and poor Dukes staging." (PMID 25272010, 2014). "Recently, UHRF1 has been classified as an oncogene that is highly expressed in many cancers." (PMID 25338120, 2014). "Several reports showed that UHRF1 may be an important biomarker for diagnosis and prognosis of cancers." (PMID 25272010, 2014). "UHRF1 plays an important role in cancer progression through epigenetic mechanisms." (PMID 23688286, 2013). "Similarly, the natural anti-cancer drug, epigallocatechin-3-gallate has been shown to induce p16INK4A re-expression-dependent pro-apoptotic pathway via the down-regulation of UHRF1 in Jurkat cells." (PMID 23688286, 2013). "UHRF1 down-regulation has been shown to induce apoptosis in cancer cells." (PMID 23688286, 2013). "UHRF1 has been shown to be upregulated in cancer of breast, prostate, pancreas, and so forth." (PMID 23320178, 2012). "Altogether, these clinical studies show that immuno-histochemical staining of UHRF1 may improve the specificity and sensitivity of current tests for cancer diagnosis." (PMID 21496237, 2011). "As a platform protein, UHRF1 is expected to be the major conductor of the epigenetic orchestra by using various executors to facilitate the conservation of the silencing marks, especially those concerning TSGs repression in the cancer cells." (PMID 21496237, 2011). "This review supports the paradigm that UHRF1 is a potential target for cancer prevention and therapy, since its repression may lead to the re-expression of TSGs, allowing cancer cells to undergo apoptosis." (PMID 21496237, 2011). "UHRF1 is up-regulated in various human cancers which may be related to its ability to sustain the transcriptional silencing of tumor suppressor genes by hypermethylation of their promoters." (PMID 22096602, 2011). "The UHRF1 is significantly overexpressed in various cancers." (PMID 20517312, 2010). "Up-regulation of UHRF1 has been reported in various cancers." (PMID 20517312, 2010). "UHRF1 over-expression has been already reported in lung and breast cancers." (PMID 19809427, 2009). "Although UHRF1 expression in muscle-invasive cancer was greater than in non-invasive (pTa) or superficially invasive (pT1) cancers, UHRF1 could still be detected by immunohistochemistry in these early-stage cancers." (PMID 19491893, 2009).
cancer (continued). "Moreover, UHRF1, an oncogene that promotes cancer cell development, induces c-Jun/AP-1 activation and transcription of inflammation/metastasis-related cytokines, facilitating cancer cell migration and invasion." (PMID 40823082, 2025). "Interestingly, analyzing the three epigenetic modifiers together, we found that the simultaneous overexpression (3 +) of at least two of the three proteins (DNMT1, G9a, and UHRF1) in cancer cells resulted in a significant shorter DFS and OS when all PDAC patients were analyzed together." (PMID 39810240, 2025). "In addition, PTMs of UHRF1 are involved in aberrant DNA methylation in cancer." (PMID 39267107, 2024). "However, UHRF1 is often overexpressed in cancers that have inactivated the RB/E2F pathway." (PMID 39051184, 2024). "However, in several types of cancers, UHRF1 is overexpressed throughout all the cell cycle phases and executes a great impact on tumorigenesis and cancer progression, with unknown mechanisms." (PMID 39341501, 2024). "Currently, no direct evidence links UHRF1 mutations to cancer." (PMID 39051184, 2024). "Furthermore, aberrant overexpression of UHRF1 altered DNA methylation patterns, thereby suppressing the gene transcription of TSGs and breaking the balance of oncogenes and TSGs, ultimately promoting cancer progression." (PMID 38725075, 2024). "However, UHRF1’s role in apoptosis varies with the cancer type." (PMID 39051184, 2024). "However, it is worthy of further studying the functional relevance of UHRF1 PTMs in cancer." (PMID 38725075, 2024). "Therefore, the inhibition of UHRF1 acetylation may become a potential anti-cancer therapeutic strategy." (PMID 38725075, 2024). "Therefore, UHRF1 can be a pragmatic/attractive anti-cancer target." (PMID 37630248, 2023). "Also, UHRF1 is frequently overexpressed in various cancers and exhibits oncogenic activity." (PMID 37573395, 2023). "Furthermore, UHRF1 upregulation in cancers also induces resistance to anticancer therapy." (PMID 37630248, 2023). "Since UHRF1 is known to interact with methyltransferase to regulate the expression of other genes, it is required to study further whether methylation and expression of UHRF1 in cancer immunity are related to T-cell dysfunction." (PMID 37460953, 2023). "Moreover, UHRF1 could be considered a potential biomarker and a therapeutic target in cancer treatments." (PMID 35996525, 2022). "Therefore, understanding how UHRF1 promotes thyroid tumor cell metastasis might be essential to retard the progression of cancer cells." (PMID 35996525, 2022). "In addition, the control of UHRF1 activity by cellular metabolites and by alternative splicing is a possible regulatory input that could be miscontrolled in cancer." (PMID 35625988, 2022). "Like DNMTs, UHRF1 may also be a potential effective target for cancer therapy." (PMID 36060265, 2022). "In addition, our results provide a potential mechanism by which UHRF1 expression may regulate tumor immunity, DNA repair, and methylation in cancer." (PMID 35656341, 2022). "UHRF1 may serve as a biomarker of immune infiltration and poor outlook of cancer." (PMID 35656341, 2022). "Besides, UHRF1 overexpression is observed in numerous cancers as is the case with EZH2, which may enable us to apply what is learnt from RB's case to other UHRF1‐overexpressing cancers if UHRF1 inhibitors can be successfully developed." (PMID 32840881, 2021). "Interestingly, several studies have reported that either UHRF1 downregulation or targeting its functional domains can act as a trigger that reactivates several TSGs and enables cancer cells to undergo apoptosis, highlighting UHRF1 as a promising target for cancer drug development." (PMID 33922029, 2021). "Thus, targeting UHRF1 and/or its partners is a promising strategy for epigenetic cancer therapy." (PMID 33922029, 2021).